TRMT1L (tRNA methyltransferase 1L)
Description:
Specifically dimethylates a single guanine residue at position 27 of tRNA(Tyr) using S-adenosyl-L-methionine as donor of the methyl groups. Dimethylation at position 27 of tRNA(Tyr) is required for efficient translation of tyrosine codons. Also required to maintain 3-(3-amino-3-carboxypropyl)uridine (acp3U) in the D-loop of several cytoplasmic tRNAs.
Synonyms: C1orf25; TRM1L; MSTP070; MST070; bG120K12.3
Tractability: PROTAC: UniProt records ubiquitination sites on it; ubiquitination databases record sites on it; its protein half-life has been measured.
Target class: Enzyme; Transferase
Gene: Protein-coding gene on chromosome 1 (185,118,085 to 185,157,072, reverse strand). Ensembl gene ENSG00000121486.
Subcellular location: Nucleus, nucleolus
Subcellular location (Human Protein Atlas): Nucleoplasm; Nucleoli
Gene Ontology:
Molecular function: protein binding; RNA binding; tRNA (guanine(27)-N2)-dimethyltransferase activity; tRNA (guanine) methyltransferase activity; catalytic activity, acting on a tRNA; S-adenosylmethionine-dependent methyltransferase activity
Biological process: tRNA N2-guanine methylation; tRNA processing
Cellular component: nucleolus; nucleus
Genetic constraint (gnomAD): Loss-of-function variants: 26 observed, 63.67 expected, observed/expected ratio (o/e) 0.41, 90% interval 0.3 to 0.57. The upper end of that interval is the gene's LOEUF score, 0.57, which puts it in group 2 of 6, group 1 being the genes least tolerant of losing a copy. Missense variants: 658 observed, 812.8 expected, observed/expected ratio (o/e) 0.81, 90% interval 0.76 to 0.86. Synonymous variants: 271 observed, 290.54 expected, observed/expected ratio (o/e) 0.93, 90% interval 0.84 to 1.03.
Homologues: Orthologues: chimpanzee TRMT1L (99% identical), macaque TRMT1L (98% identical), dog TRMT1L (94% identical), guinea pig TRMT1L (91% identical), pig TRMT1L (91% identical), mouse Trmt1l (88% identical), rat Trmt1l (86% identical), rabbit TRMT1L (80% identical), zebrafish trmt1l (55% identical), tropical clawed frog trmt1l (53% identical). Paralogues in human: TRMT1 (15% identical).
Diseases named in the same sentence as TRMT1L in open-access papers:
TRMT1L is named in the same sentence as 3 diseases in open-access papers, as found by Europe PMC text mining. Sharing a sentence is not in itself a finding about the gene and the disease. The quoted sentences say what the papers report.
tumor (3 papers, 2020 to 2024). "We pooled all 20 genes (Stx6, Ramp1, Traf3ip1, Nckap5, Pfkfb2, Trmt1l, Rprd1b, Rer1, Sepsecs, Rhobtb1, Tsen15, Abcc3, Arid5b, Tnr, Dock2, Tti1, Fam81a, Oxr1, Plxna2 and Tbc1d31) together as the mouse tumour susceptibility gene signature (mTSGS)." (PMID 39067134, 2024). "Multivariate Cox regression analysis identified SNPs in 8 genes (Stx6, Ramp1, Traf3ip1, Nckap5, Pfkfb2, Trmt1l, Rprd1b, and Rer1) that were independently associated with age of tumour onset." (PMID 39067134, 2024). "The results showed that the expression levels of seven tRNA-modifying genes (FTSJ1, ADAT1, U13, RNMTL1, TRDMT1, METTL14, and TRMT1L) in NSCLC tumor tissues were significantly lower than that in normal tissues (all P values < 0.05)." (PMID 32393790, 2020). "Multivariate analyses flagged SNPs in 20 genes (Stx6, Ramp1, Traf3ip1, Nckap5, Pfkfb2, Trmt1l, Rprd1b, Rer1, Sepsecs, Rhobtb1, Tsen15, Abcc3, Arid5b, Tnr, Dock2, Tti1, Fam81a, Oxr1, Plxna2, and Tbc1d31) independently tied to various tumour characteristics, designated as a mTSGS." (PMID 39067134, 2024).
TRMT1L also shares sentences with these, for which no sentence is quoted: breast cancer (3 papers); cancer (1).